PARP6 (poly(ADP-ribose) polymerase family member 6)
Diseases named in the same sentence as PARP6 in open-access papers:
PARP6 is named in the same sentence as 26 diseases in open-access papers, as found by Europe PMC text mining. Sharing a sentence is not in itself a finding about the gene and the disease. The quoted sentences say what the papers report.
breast carcinoma (11 papers, 2019 to 2025). "The oncogenic role of PARP6 has also been described in breast cancer, where pharmacological inhibition of PARP6 promotes apoptosis of cancer cells in vitro." (PMID 41463260, 2025). "Correspondingly, PARP6 specific inhibitor AZ0108 induced the multipolar spindle phenotype to result in apoptosis of breast cancer cells." (PMID 38734665, 2024). "By screening a library of compounds for the ability to induce mitotic defects, researchers have identified AZ0108 as a potent PARP6 inhibitor, which exerts antitumor effects in vivo and induces cell death in breast cancer cells in vitro." (PMID 35652091, 2022). "A report on breast cancer indicated that PARP6 can directly target ADP-ribosylate Chk1, leading to the multipolar spindle formation and apoptosis induction." (PMID 35836822, 2022). "By screening a collection of compounds for their ability to induce mitotic defects, AZ0108 was identified as a potent ARTD17/PARP6 inhibitor, which has been proved, leading to apoptosis in a subset of breast cancer cells in vitro and antitumor effects in vivo." (PMID 33440786, 2021). "About their pathological roles, particularly in cancer diseases, PARP6 contributes to the maintenance of centrosome integrity by MARylating the checkpoint kinase and promoting the breast cancer growth, while PARP15 is overexpressed in B-aggressive lymphoma and acute myeloid leukemia." (PMID 37570820, 2023). "However, pharmacological inhibition of PARP6 triggered multipolar spindle formation and led to apoptosis in a subset of breast cancer cells and antitumor effects." (PMID 36845744, 2023). "On the other hand, new studies showed that PARP6 could maintain centrosome integrity via the direct MARylation of Chk1 and modulation of its activity in breast cancer cells." (PMID 31500199, 2019). "Treatment with AZ0108, a PARP6 inhibitor, led to apoptosis in a subset of breast cancer cells." (PMID 31500199, 2019). "PARP6, a mono-ADP-ribose generating enzyme, directly MARylates Chk1 kinas which involved in regulating centrosome functions to promote tumorigenesis in breast cancer." (PMID 38734665, 2024). "Poly (ADP-ribose) polymerase 6 (PARP6) belongs to the PARP family, which plays a crucial role in numerous cancers, such as gastric and colorectal adenocarcinoma and breast cancers." (PMID 35836822, 2022). "PARP6 suppression, either by the PARP inhibitor AZ0108 or small interfering RNA (siRNA)-mediated knockdown, promotes an anti-tumor response in a panel of breast cancer lines as well as in breast cancer xenografts, likely through the MARylation of CHK1 during mitosis." (PMID 40741921, 2025). "Although not specific, its anti-MDA-MB-468 breast cancer activity, in xenograft models, seems directly related to the PARP6 inhibition, which is responsible for blocking the centrosome clustering and inducing multipolar spindle." (PMID 37570820, 2023).
colorectal cancer (11 papers, 2015 to 2025). A primary or metastatic malignant neoplasm that affects the colon or rectum. "High levels of PARP6 inversely correlate with tumor growth and are associated with good prognosis in colorectal carcinoma (CRC)." (PMID 40741921, 2025). "PARP6 also plays a key role in suppressing colorectal cancer progression and its protein expression in human colorectal cancer was linked to a good prognosis." (PMID 31500199, 2019). "However, Parp6 has been shown to be a negative regulator of cell proliferation function via downregulation of Survivin in colorectal cancer and high PARP6 expression has been correlated with better tumor cell differentiation." (PMID 36765634, 2023). "For instance, PARP6 is expressed at low levels in colorectal cancer." (PMID 34319912, 2021). "However, it is still unclear that PARP6 function besides growth suppression in colorectal cancer (CRC)." (PMID 26934315, 2016). "Indeed, according to both immunohistochemical and Kaplan–Meier analysis, PARP6-positive colorectal cancer correlated with a good prognosis, supporting a role of PARP6 as a tumour suppressor through its involvement in cell-cycle control and apoptosis induction (Refs 54, 55)." (PMID 39189367, 2024). "However, PARP6 shows a duality, acting differently on the expression and stability of the Survivin protein, proliferation, and migration, in one case as an oncoprotein in gastric cancer models, and conversely, acting as a suppressor protein of malignancy in colorectal cancer models." (PMID 41463260, 2025). "PARP6 expression is a biomarker for good prognosis of colorectal cancers (CRC) and the increased methylation of PARP6 is positively correlated with poor prognosis of hepatoblastoma, indicating the tumor suppressor role of PARP6." (PMID 36035988, 2022). "PARP6 is a member of the PARP family, which is a tumor suppressor in colorectal cancer." (PMID 35836822, 2022).
hepatocellular carcinoma (6 papers, 2021 to 2025). A malignant tumor that arises from hepatocytes. "PARP6 is expressed at low levels in hepatocellular carcinoma (HCC), and its expression is negatively correlated with tumor differentiation." (PMID 40904702, 2025). "While SIRT3 was found to be a novel regulator of cardiovascular disease, and PARP6 has suggested inhibiting the development of hepatocellular carcinoma and intestinal cancer." (PMID 36439178, 2022). "The role of PARP6 in hepatocellular carcinoma (HCC) cells is inconsistent with that in GC." (PMID 34976832, 2021). "ARTD17/PARP6, considered as a tumor suppressor, limits the proliferation and spreading ability of the hepatocellular carcinoma cells by degrading XRCC6/Ku70 and by regulating the Wnt/ß-catenin pathway." (PMID 33440786, 2021). "PARP6 was confirmed can inhibit the expression of XRCC6 by inducing degradation and thus regulate the Wnt/β-catenin pathway, which contributes to the suppression of hepatocellular carcinoma." (PMID 36845744, 2023). "In addition, PARP6 reportedly inhibits XRCC6 expression by inducing degradation and thus affects the Wnt/β-catenin signaling pathway, leading to the suppression of hepatocellular carcinoma." (PMID 35836822, 2022).
hepatoblastoma (3 papers, 2016 to 2022). Hepatoblastoma (HB) is a malignant hepatic tumor and is the most common pediatric liver cancer. "Recently, it has been shown that hypermethylation of PARP6 was found in hepatoblastoma and was well correlated with poor prognosis (Meeting abstract in Nihon Geka Gakkai Zasshi 115, p308, 2014 [in Japanese])." (PMID 26934315, 2016). "Limited genome-wide methylation analysis by HM450 found that differentially methylated genes were involved with liver cell differentiation and cancer, and four tumor suppressor genes (GPR180, MST1R, OCIAD2, and PARP6) were potentially related to progression in hepatoblastomas." (PMID 36212481, 2022).
gastric cancer (2 papers, 2021 to 2024). A primary or metastatic malignant neoplasm involving the stomach. "However, a later paper, suggested that PARP6 positively regulates Survivin in gastric cancer, with higher expression of PARP6 showing a strong correlation with increased carcinogenic cell properties including: motility, proliferation, migration and invasion." (PMID 35096828, 2021).
glioblastoma (2 papers, 2025). The most malignant astrocytic tumor (WHO grade IV). "PARP6-s expression enhances NF-κB activation, ultimately promoting the glioblastoma mesenchymal phenotype." (PMID 40741921, 2025). "In glioblastoma, arginine/serine-rich protein 1 (RSRP1) catalyzes PARP6 exon 18 skipping, generating the truncated oncogenic form of PARP6 (PARP6-s), which lacks the catalytic triad of residues essential for MARylating activity." (PMID 40741921, 2025).
diphtheria (1 paper, 2016). A Gram-positive bacterial infection caused by Corynebacterium diphtheriae. "PARP6 (Poly (ADP-Ribose) Polymerase Family, Member 6) is a protein-coding gene and is associated with diphtheria." (PMID 26930047, 2016).
epilepsy (1 paper, 2021). A brain disorder characterized by episodes of abnormally increased neuronal discharge resulting in transient episodes of sensory or motor neurological dysfunction, or psychic dysfunction. "We also report PARP6 mutations in six patients with several neurodevelopmental disorders, including microencephaly, intellectual disabilities, and epilepsy." (PMID 34067418, 2021). "During the course of our mouse study, six patients with mutations in PARP6 were identified, showing different degrees of developmental delay, learning disabilities, and epilepsy." (PMID 34067418, 2021).
glioma (1 paper, 2023). A benign or malignant brain and spinal cord tumor that arises from glial cells (astrocytes, oligodendrocytes, ependymal cells). "According to the results of qRT-PCR, the mRNA expressions of CD38, NADK, PARP9 were significantly elevated in glioma tissues compared with NBT, while the mRNA expressions of NAPRT and PARP6 showed a significant downward trend in glioma tissues." (PMID 36845744, 2023). "The NMRGS score of every glioma patient was obtained as follows: NMRGS score = (-0.28992*CD38 expression) + (0.38315*NADK expression) + (-0.04654*NAPRT expression) + (0.2211*NMNAT3 expression) + (-0.24486*PARP6 expression) + (0.29991*PARP9 expression)." (PMID 36845744, 2023).
intellectual disabilities (1 paper, 2021). "Often, MCPH individuals have intellectual disability, language delay, and varying degrees of motor function delay —clinical features seen in the patients with PARP6 mutations." (PMID 34067418, 2021).
lymph node metastasis (1 paper, 2016). "Low expression of PARP6 was significantly correlated with malignant behaviors including lymph node metastasis, histological differentiation and tumor staging." (PMID 26934315, 2016).
tumor (14 papers, 2016 to 2025). "Collectively, these findings demonstrate a central role of PARP6 in cancer development and a novel drug target selective for a subset of tumours." (PMID 39189367, 2024). "PARP6 has been shown to be involved in the genesis of different tumours; however, its mechanism of action is still controversial and not completely characterised." (PMID 39189367, 2024). "Conversely, within the top 20 upregulated genes, our treatment had significant long-term effects on the tumor suppressors Lman1I, Clec4e, and Parp6." (PMID 36765634, 2023). "The results showed that the tumor size and volume were significantly (P < 0.01) decreased in lenti-PARP6 xenografts or sh-SNHG1 + lenti-PARP6 xenografts compared to those in the model (control) group." (PMID 35836822, 2022). "CRC cases with high expression of PARP6 and low expression of Survivin significantly decreased the lymph node metastasis, histological differentiation and delayed tumor progression." (PMID 26934315, 2016). "In conclusion, we found that PARP6 has tumor suppressive roles in CRC via inhibition of cell growth, migration and invasion and promotion of apoptosis." (PMID 26934315, 2016). "On the other hand, CRC cases with low expression of PARP6 and high expression of Survivin significantly increased lymph node metastasis, histological differentiation and promoted tumor progression." (PMID 26934315, 2016). "Given the importance of vault particles in RNA transport, PARP4 must be considered a regulator of the immune response during embryonic development, detoxification of toxins in adult brains, being shared with PARP6, and resistance of tumor cells to different drugs." (PMID 41463260, 2025). "Collectively, we speculated that PARP6 may act as a tumor suppressor in HSCC, which is a functional target of SNHG1." (PMID 35836822, 2022). "Our findings reveal that SNHG1 is a key regulator in HSCC and may contribute to tumor development via targeting PARP6." (PMID 35836822, 2022). "PARP6 is a novel member, and our previous findings suggest that PARP6 may act as a tumor suppressor via suppressing cell cycle progression." (PMID 26934315, 2016). "In summary, PARP6 acts as a tumor suppressor via downregulating Survivin expression in CRC." (PMID 26934315, 2016). "Our previous findings suggest that PARP6 may act as a tumor suppressor via suppressing cell cycle progression." (PMID 26934315, 2016). "Moreover, we examined the tumor suppressive function of PARP6 in CRC cells both in vitro and in vivo." (PMID 26934315, 2016). "PARP6 and PARP10: This ambiguous role in tumor repression and progression is also observed in PARP6 and PARP10." (PMID 41463260, 2025). "Gene chip analysis combined with experimental verification has confirmed that PARP6 inhibits XRCC6 expression by inducing its degradation, thereby suppressing the Wnt/β‐catenin pathway, which contributes to tumor suppression in HCC." (PMID 40904702, 2025). "HNSCC: SNHG1 inhibition ↑PARP6 → suppresses tumor growth/migration; HCC: Low PARP6 → HDM2‐mediated XRCC6 degradation → ↑Wnt signaling → promotes progression." (PMID 40904702, 2025). "Similar to ARTD17/PARP6, the arginine-specific eraser ARH1 also seems to harbor tumor-protective potential." (PMID 33808662, 2021). "Another research indicated that the four novel tumor suppressor candidates including GPR180, MST1R, OCIAD2, and PARP6 were potentially useful molecular markers for predicting poor prognosis in HB patients." (PMID 33312943, 2020). "To know the tumor suppressive roles of PAPR6 in CRC cells, we used a full-length PARP6 (FL-PARP6) and C-terminal deletion mutant PARP6 (ΔC-PARP6)." (PMID 26934315, 2016). "In other cases, such as PARP6 and PARP10, there is controversy as to whether we are dealing with a role in tumor repression and progression." (PMID 41463260, 2025).
tumor (continued). "The authors speculated that it may be after a relapse of B-ALL, the up-regulation of three metabolic genes of NADSYN1, PARP6 and SIRT3, was promoted in response to certain tumor factors." (PMID 36439178, 2022). "Tumor suppressors L1TD1 and PARP6, also the specific ESGs of TIME-1, and their methylation may promote tumor proliferation and low immune infiltration." (PMID 33407585, 2021). "In contrast to ARTD10, ARTD14 and ARTC1 which are likely to promote tumor growth, ARTD17/PARP6 was reported to be a negative regulator of cell proliferation and forced expression of ARTD17 in HeLa resulted in growth suppression and accumulation of cells in the S-phase." (PMID 33808662, 2021). "Therefore, to know the tumor suppressive function of PARP6, the mechanism of suppression of ERK and Akt activity by PARP6 are required to be clarified." (PMID 26934315, 2016).
cancer (11 papers, 2016 to 2025). A tumor composed of atypical neoplastic, often pleomorphic cells that invade other tissues. "SIRT3 has far-reaching effects on nuclear gene expression, cancer, cardiovascular disease, neuroprotection, aging, and metabolic control.PARP6 enables protein ADP-ribosylase activity." (PMID 36439178, 2022). "It has been described that knockdown of PARP6 promotes cell apoptosis as it is acting as an oncogene in different types of cancers." (PMID 35806438, 2022). "In this review, we summarize the role and regulatory mechanism of PARP3, PARP4, and PARP6–16 in cancer." (PMID 34976832, 2021). "This anti-apoptotic property is largely suggested to be why high expression of Survivin is correlated with cancer and tumourigenesis, implicating PARP6 as a tumour suppressor." (PMID 35096828, 2021). "PARP6 has also recently been characterized by varying expression levels in different cancers, which is hypothesized to be due to a difference in role depending on the tissue type." (PMID 37508568, 2023). "AZO108 may highlight the importance of understanding and targeting other PARP members in anticancer treatments, but the type of cancer being treated, and its relationship with PARP6, must first be understood." (PMID 37508568, 2023). "The association between Chk1 and PARP6 has been reported in BC as well, highlighting the importance of the ATR-Chk1 pathway and providing further evidence supporting PARPs as potential therapeutic targets in cancer." (PMID 34976832, 2021). "This provides strong evidence that it could be worthwhile investigating targeting PARP6 for cancer therapy in the future." (PMID 35096828, 2021). "Intriguingly, recent studies show that Parp6 knockdown, or inhibition with a small molecule inhibitor (i.e., AZ0108), in cancer cells induces multipolar spindle formation." (PMID 34067418, 2021). "In GC, PARP6 expression is higher in cancer tissues and cells than in normal gastric mucosa tissues and cells." (PMID 34976832, 2021). "PARP6 and PARP10 have both promoting and suppressive effects on cancer development." (PMID 34976832, 2021). "Recent developments in enzymatic approaches to obtain ADP-modified peptides by PARP6, PARP3, PARP14, and PARP10 in human and murine diseases are advancing our ability to generate site-specific MAR antibodies, with future application in animal models of cancer and neurodegenerative diseases." (PMID 41463260, 2025).
neurodevelopmental disorder (2 papers, 2016 to 2021). A behavioral and cognitive disorder with onset during the developmental period that involves impaired or aberrant development of intellectual, motor, or social functions. "Elucidating the mechanism by which PARP6-mediated MARylation controls dendritic complexity will not only provide new insight into how dendrite morphogenesis is regulated during development, but could also lead to new therapeutic approaches for neurodevelopmental disorders." (PMID 26725726, 2016).
adenocarcinoma (1 paper, 2016). A common cancer characterized by the presence of malignant glandular cells. "We observed that the PARP6-positive cells were particularly observed in the cytoplasm of well differentiated adenocarcinoma, but not in poorly differentiated adenocarcinoma." (PMID 26934315, 2016).
PARP6 also shares sentences with these, for which no sentence is quoted: cardiovascular disease (2 papers); colorectal adenocarcinoma (2); and heart disorders (1); diabetes (1); Hypopharyngeal Squamous Cell Carcinoma (1); intestinal cancer (1); ischemia (1); lentivirus infection (1); lipodystrophy (1); microencephaly (1); Stroke (1).